MAOB (monoamine oxidase B)
Diseases named in the same sentence as MAOB in open-access papers (continued):
Sharing a sentence is not in itself a finding about the gene and the disease.
hepatoma (9 papers, 2020 to 2025). "Paradoxically, MAOB exhibits tumor-suppressive effects in endometrial cancer and hepatocellular carcinoma, while its loss promotes renal and bladder cancer progression." (PMID 40821817, 2025). "On the other hand, the CYP3A4 gene is also highly expressed in the liver and is involved in maintaining the concentration of GGA when the MAOB gene is deficient, thus it is expected to have an inhibitory effect on hepatoma." (PMID 35208214, 2022). "Additionally, they speculated that the synthesis of “MAOB” might be specifically repressed in hepatoma and proposed that a deficiency of “MAOB” activity in mitochondria is a reflection of an early stage of the carcinogenic process." (PMID 34564450, 2021). "Up to the present, there have been several reports of reduced MAO activity in the hepatoma area, which is considered MAOB activity." (PMID 34564450, 2021). "Suppression of MAOB activity by either MAO inhibitor TCP or MAOB siRNA significantly reduced endogenous GGA levels in human hepatoma cells." (PMID 32094232, 2020). "As a third step, we knocked out the MAOB gene in the hepatoma cell and attempted to deplete the intracellular GGA, but we failed to deplete it using the KO method." (PMID 32094232, 2020). "By using an MAO inhibitor and siRNAs to inhibit and downregulate the cellular MAOB enzyme activity, here, we demonstrate that hepatic MAOB is involved in the maintenance of the intracellular GGA level in human hepatoma-derived cells." (PMID 32094232, 2020). "We are now quite confident that MAOB is a putative enzyme responsible for biosynthesis of GGA in human hepatoma cells." (PMID 32094232, 2020). "Unexpectedly, however, CRISPR/Cas9-generated MAOB-KO human hepatoma Hep3B cells had GGA levels similar to those in MAOB-WT cells." (PMID 32094232, 2020). "From these results, we conclude that a MAOB-mediated metabolic pathway is a primary process for maintaining the cellular GGA level in human hepatoma cells." (PMID 32094232, 2020). "In conclusion, herein, we show that MAOB is principally involved in GGA biosynthesis through oxidation of GGOH in human hepatoma cells." (PMID 32094232, 2020). "Furthermore, when the prognosis of patients with hepatocellular carcinoma is compared between the high and low MAOB gene expression groups, the survival rate of the high MAOB gene expression group is higher." (PMID 35208214, 2022). "Recently, we found that monoamine oxidase B (MAOB) catalyzed the oxidation of geranylgeraniol (GGOH) to produce geranylgeranial (GGal), a direct precursor of endogenous GGA in hepatoma cells, using tranylcypromine, an inhibitor of MAOs, and knockdown by MAOB siRNA." (PMID 35208214, 2022). "We previously investigated the GGOH oxidation activity of each subcellular fraction in human hepatoma-derived HuH-7 cells, and reported that in addition to the mitochondrial fraction where MAOB is localized, GGOH oxidation activity was also present in the microsomal fraction." (PMID 35208214, 2022). "However, the enzymatic activity of MAOB is decreased at the site of hepatoma, and a classical paper described that the higher the grade of hepatoma, the lower the activity of MAOB." (PMID 35208214, 2022). "To ensure that MAOB is involved in GGA biosynthesis more reliably, we performed KO of the MAOB gene using the CRISPR/Cas9 plasmids in human hepatoma cells, but, unexpectedly, the intracellular GGA content of MAOB- KO cells was almost the same as that of the WT cells." (PMID 32094232, 2020). "Here, using two human hepatoma cell lines, we investigated whether MAOB contributes to GGA biosynthesis." (PMID 32094232, 2020). "Furthermore, the biosynthesis of GGA from mevalonic acid in mammals including humans was confirmed by isotopomer spectral analysis using 13C-labeled mevalonolactone and cultured hepatoma cells, and the involvement of hepatic monoamine oxidase B in the biosynthesis of GGA was also demonstrated." (PMID 37247782, 2023).
hepatoma (continued). "Interestingly, back-transfection of the MAOB gene into Hep3B/MAOB-KO cells completely restored the MAOB siRNA-mediated reduction of endogenous GGA, strongly suggesting that the MAOB gene is the enzyme primarily responsible for maintenance of the endogenous GGA level in human hepatoma cells." (PMID 32094232, 2020). "In studies of enzymes involved in GGA biosynthesis, we very recently reported that monoamine oxidase B (MAOB) plays an important role in the biosynthesis of GGA using HuH-7 and Hep3B cells derived from human hepatoma." (PMID 35208214, 2022). "Hep3B cells, a cell line derived from human hepatocellular carcinoma, have been found to have almost the same concentration of endogenous GGA, 11.7 pmol/g in wild-type cells and 12.5 pmol/g in MAOB knockout cells." (PMID 35208214, 2022). "In human hepatoma cells, suppression of MAOB activity significantly decreased endogenous levels of geranylgeranoic acid (GGA), an agent that prevents secondary primary hepatoma through oxidation of geranylgeraniol." (PMID 34209963, 2021). "Lastly, it has been shown that hepatic monoamine oxidase B (MAOB) is involved in the biosynthesis of geranylgeranoic acid (GGA) (found in animal models and hepatoma cell lines) which is believed to prevent hepatocarcinogenesis." (PMID 35008267, 2021). "A reaction that oxidizes GGOH to GGal showed Michaelis-Menten-type kinetics and the Km value of the recombinant human MAOB was calculated to be 34.34 ± 5.35 μM for GGOH, which is in the range of those of rat hepatic and human hepatoma GGOH oxidase." (PMID 32094232, 2020). "Therefore, MAOB and CYP3A4, which are alternatively involved in the biosynthesis of hepatic GGA, are both hepatoma suppressive genes." (PMID 35208214, 2022). "Here, we can reasonably speculate that the decrease in hepatic MAOB activity induces a decrease in endogenous GGA levels in the liver, allowing cells in the carcinogenic stage to escape GGA-induced cell death and leading to the development of spontaneous hepatomas." (PMID 34564450, 2021). "Because MAOB-KO cells could not be established in HuH-7 cells by puromycin selection after several trials, another human hepatoma-derived cell line, Hep3B, which does not harbor any translocation in the X chromosome, was used because the MAOB gene is located on the X chromosome." (PMID 32094232, 2020). "In this review, based mainly on our published papers, we have shown that hepatic monoamine oxidase B is involved in the biosynthesis of GGA and that GGA induces cell death in human hepatoma-derived cell lines by noncanonical pyroptosis, one of the mechanisms of sterile inflammatory cell death." (PMID 37247782, 2023).
memory impairment (9 papers, 2014 to 2025). "Astrocytic GABA and H2O2 are associated with memory impairment in AD and synthesized through the Monoamine Oxidase B (MAOB)-mediated multi-step degradation of putrescine." (PMID 39815261, 2025). "Evidence from prior studies suggests that Put has the ability to produce GABA via the enzyme MAO-B (monoamine oxidase B) in astrocytes, which may pose a risk for memory impairment." (PMID 38049863, 2023). "Due to the involvement of monoamine oxidase B (MAO-B) in the formation of reactive oxygen species (ROS) and the association of high acetylcholinesterase (AChE) levels with learning and memory impairment, a common strategy is to design inhibitors against the former enzymes." (PMID 39338334, 2024).
prostate carcinoma (9 papers, 2014 to 2025). A carcinoma that arises from epithelial cells of the prostate gland. "However, the functional role of MAOB and impacts of its genetic variants on prostate cancer (PCa) is unknown." (PMID 38520217, 2024). "Odds ratios (ORs) and 95% confidence intervals (CIs) of the clinical status and MAOB rs1799836 and rs3027452 genotypic frequencies in 702 patients with prostate cancer." (PMID 38520217, 2024). "MAOB can also be used as a novel target for the treatment of prostate cancer and presents differential expression in oral tumors." (PMID 34819038, 2021). "Distribution frequency of MAOB genotypes in 702 patients with prostate cancer." (PMID 38520217, 2024). "MAOB is regarded as a novel biomarker for accurate prostate cancer diagnosis and treatment." (PMID 33845800, 2021). "Computational biology and in vivo verification have elaborated on the potential of MAOB to activate the CXCR4-Src/JNK signaling pathway, eventually aiding in the growth and progression of prostate cancer." (PMID 39000203, 2024). "None of the prostate cancer cell lines expressed appreciable levels of MAOB." (PMID 25198178, 2014).
Hypertension (8 papers, 2020 to 2025). The presence of chronic increased pressure in the systemic arterial system. "In the present work we have found an association between a polymorphic variant of MAOB gene and arterial hypertension in obese hypogonadic patients." (PMID 31743621, 2020). "We have found an association between a polymorphic variant of MAOB gene and arterial hypertension in obese hypogonadic patients." (PMID 31743621, 2020). "In this study we report a strong association of the polymorphism rs3027452 of the MAOB with essential hypertension in hypogonadic patients." (PMID 31743621, 2020). "Additionally, apart from its association with neurodegenerative diseases, the rs3027452 A‐allele was reported to be linked to lower MAOB activity and a correlation with blood pressure in obese hypogonadic patients with hypertension." (PMID 38520217, 2024). "Pargyline is an irreversible selective monoamine oxidase B inhibitor and used to treat hypertension." (PMID 35105345, 2022).
mood disorder (7 papers, 2017 to 2024). A cognitive disorder a disturbance in which the person's mood is hypothesized to be the main underlying feature. "Monoamine oxidase-B (MAO-B) inhibitors have been used as treatment for MDD and other mood disorders for a long time." (PMID 32088835, 2020).
psychosis (7 papers, 2014 to 2024). "MAOB rs1799836 was also associated with MHPG concentrations in men with psychosis (uncorrected p = 0.001) in the present study." (PMID 25073638, 2014). "This is also true for other PD medications, such as dopamine agonists or MAO-B (monoamine oxidase B) inhibitors that may induce psychosis." (PMID 37569510, 2023).
tauopathies (7 papers, 2019 to 2023). "Nevertheless, due to the off-target binding to monoamine oxidase-B (MAO-B), the THK family tracers are deemed to have limited utility in imaging tauopathies in AD." (PMID 35685772, 2022). "Their first generation only detected tau lesions in AD and not in primary tauopathies, and many turned out to have high affinities for nonamyloids, such as monoamine oxidase B." (PMID 37163602, 2023). "However, tracers in this family were later found to have notable off-target binding to monoamine oxidase-B (MAO-B), which greatly limited their utility in imaging of tauopathies including AD." (PMID 34025386, 2021).
breast carcinoma (6 papers, 2014 to 2026). "MAOB was recognized in a gene signature that characterizes mammary stem cells, and its expression is a prognostic factor in breast cancer." (PMID 34378323, 2021). "Of interest, the administration of L-deprenyl, an inhibitor of MAOB, resulted in significant reductions in tumor incidence in a rodent model of carcinogen-induced breast cancer." (PMID 25198178, 2014). "The response to hormone stimulus and the response to lipids include Lox and MAOB together with ESR1, suggestive of the presence of common activator of estrogen positive type of breast cancer." (PMID 29261141, 2017).
endometrial carcinoma (6 papers, 2021 to 2025). A malignant tumor arising from the epithelium that lines the cavity of the uterine body. "A previous study found that miR-522 accelerates the progression of endometrial cancer by inhibiting MAOB." (PMID 41430255, 2025). "In human endometrial carcinoma cells, MAOB is downregulated by high expression of miR-522 and accelerates the progression of endometrial carcinoma." (PMID 34209963, 2021).
autism (5 papers, 2013 to 2020). Persistent deficits in social interaction and communication and interaction as well as a markedly restricted repertoire of activity and interest as well as repetitive patterns of behavior. "This work aims to study the association between autism and MAOA uVNTR, MAOB rs1799836, and DRD2 TaqI A. Also the study analyzed genomic sequence variations of miR-431 and miR-21." (PMID 24453887, 2013). "This work studied the association of autism with genetic variations in neurotransmitter-related genes, including MAOA uVNTR, MAOB rs1799836, and DRD2 TaqI A in 53 autistic patients and 30 healthy individuals." (PMID 24453887, 2013). "At that time, according to the GP model of autism, ASD symptoms could have been masked by genetic variants such has low-COMT polymorphism, or immature MAOB enzyme, or DA overexpression." (PMID 33262691, 2020). "So far, no available information was found regarding relation of MAOB polymorphism and autism; however, this study highlighted the importance of G allele in both male and female autistic patients." (PMID 24453887, 2013). "In the Guided Propagation (GP) model of autism, monoaminergic equilibrium tends to continue if COMT is poorly expressed, if X-inactivation occurs (in women), and until MAOB is fully operational (around 2 years after birth)." (PMID 33262691, 2020).
cognitive decline (5 papers, 2021 to 2025). "For instance, in the GiD reactive astrocyte model, an excessive generation of hydrogen peroxide by monoamine oxidase B (MaoB) has been observed, subsequently giving rise to tautopathy, glial activation, neuronal death, brain atrophy, and cognitive decline." (PMID 37891935, 2023).
delirium (5 papers, 2021 to 2025). A disorder characterized by confusion; inattentiveness; disorientation; illusions; hallucinations; agitation; and in some instances autonomic nervous system overactivity. "Differences in the activity of MAOB in surgical delirium-prone patient population were indicated by a change in the concentration of PEA as well as polyamines." (PMID 34017039, 2021). "Differences in the activity of MAOB in the surgical delirium-prone patient population was indicated by a change in the concentration of PEA as well as polyamines." (PMID 34017039, 2021). "The metabolomic data and symptom similarities of delirium prone patients from a surgical setting and COVID-19 patients indicate potential dysfunction in MAOB." (PMID 34017039, 2021). "Further analysis is currently under way to explore in greater detail the role of MAOB in delirium and SARS-CoV-2 infection with further exploration of the effects of sex and other demographic, medical or drug utilization on the delirium related metabolic changes." (PMID 34017039, 2021). "The over-activity of MAOB can result in the observed PEA concentration decrease and the major changes observed in the polyamines as well as related amino acids in the delirium-prone patients." (PMID 34017039, 2021).
epilepsy (5 papers, 2019 to 2026). A brain disorder characterized by episodes of abnormally increased neuronal discharge resulting in transient episodes of sensory or motor neurological dysfunction, or psychic dysfunction. "The second, P915, was a female monozygotic twin born at 35 weeks reported with spastic diplegia, epilepsy and visual problems while her twin was developmentally normal despite also carrying the MAOB variant." (PMID 31700678, 2019).
lung carcinoma (5 papers, 2016 to 2026). "Integrating Sc-RNA sequencing, RT-qPCR and KM plots, we identified MAOB as a key gene of GGO-associated lung cancer." (PMID 38434969, 2024). "In conclusion, this study represents the first comprehensive utilizing metabolomics, transcriptomics, and Sc-RNA sequencing, to identify unique metabolite-associated gene signature, disrupted histidine metabolism, and pinpoint MAOB as a key gene in GGO-associated lung cancer." (PMID 38434969, 2024). "To detect the impact of MAOB on the proliferation of lung cancer in vivo, we constructed a xenograft model on nude mice." (PMID 38434969, 2024). "Immunohistochemical (IHC) assays derived from the Human Protein Atlas (HPA) and clinical GGO samples showed that the protein expression of MAOB was obviously reduced in lung cancer." (PMID 38434969, 2024). "Meanwhile, we generated KM plots based on prognostic data from Kaplan-Meier Plotter and only CYP3A5 and MAOB showed consistent pattern of gene expression and prognosis, which genes with lower expression in lung cancer were correlated with a better prognosis." (PMID 38434969, 2024). "However, few have suggested a role for MAOB inhibitors in the context of radiotherapy for lung cancer." (PMID 26906215, 2016). "Western blot assays further demonstrated lung cancer cell lines expressed a lower protein level of MAOB than normal bronchial epithelial cells." (PMID 38434969, 2024). "Although MAOB is known to be expressed in pulmonary tissues, its function in lungs and the clinical implication of its expression in lung cancer have not been determined." (PMID 26906215, 2016).
oral cancer (5 papers, 2014 to 2025). "Compared to healthy controls, patients with risk polymorphisms of MAOA, MAOB, and COMT had a significantly enhanced risk of oral cancer." (PMID 34209963, 2021). "To confirm the differences in the distribution of MAOA, MAOB, and COMT among male patients with oral cancer (n = 209), pharyngeal cancer (n = 88), OPMD (n = 40), and control (n = 193), we divided the patients into four groups." (PMID 34209963, 2021). "A similarly significant pattern was confirmed in the distribution of candidate genotypes of MAOA, MAOB, and COMT among men with oral cancer (n = 209), pharyngeal cancer (n = 88), and OPMD (n = 40), and controls (n = 193)." (PMID 34209963, 2021). "This study provides novelty by showing that mRNA levels of MAOB, NAB2, COL3A1, NPIPB4, CYP27A1, and SIAE were significantly reduced in the saliva of oral cancer patients." (PMID 31963366, 2020). "Additionally, in oral cancer cell lines (OECM-1 and HSC-3), compared to the control group, downregulation of MAOB mRNA and protein was found to be statistically significant after arecoline treatment (p < 0.05)." (PMID 34209963, 2021). "MAOB mRNA levels in human saliva were significantly downregulated in the oral cancer group compared to the non-tumor control group, suggesting its use as a potent biomarker for early detection of oral cancer." (PMID 34209963, 2021).
Tremor (5 papers, 2021 to 2023). An unintentional, oscillating to-and-fro muscle movement about a joint axis. "Similarly, the effect of MAOB inhibitors on tremor-related circuits and cerebellum is also unclear, and further investigations are needed." (PMID 35750692, 2022). "However, antidepressant drugs, such as serotonin reuptake inhibitors (SSRI), combined with anti-Parkinson drugs, such as monoamine oxidase B inhibitors (MAO-BI), can easily aggravate tremor symptoms." (PMID 35186098, 2022).
anxiety disorder (4 papers, 2012 to 2025). A category of psychiatric disorders which are characterized by anxious feelings or fear often accompanied by physical symptoms associated with anxiety. "This is an important finding because MAOB has been implicated in mood and anxiety disorders including social phobia, panic disorder and post-traumatic stress disorder (PTSD)." (PMID 23152871, 2012).